NF1 (neurofibromin 1)
Diseases named in the same sentence as NF1 in open-access papers (continued):
Sharing a sentence is not in itself a finding about the gene and the disease.
glioma (continued). "Next, we proceeded to test the effect of ATRX loss in glioma cells developing in patients with NF1, which are ATRX wildtype and lack ALT." (PMID 35740680, 2022). "Additional studies and clinical trials are needed to further define the underlying biologic nature of NF1-associated gliomas and determine optimal treatment strategies for affected patients." (PMID 35945463, 2022). "NF1 germline mutations have been described in high glioma pediatric patients, affecting the splicing process as c.1641+2T>A and c.4174-2>AG in glioblastoma and anaplastic astrocytoma (AA), respectively." (PMID 36497448, 2022). "The most common non-FGFR1 alterations were IDH1/2 mutations (234 cases), KIAA1549-BRAF fusion (73 cases), 24 TERT C228/C250-mutated gliomas and 35 cases with NF1." (PMID 35018490, 2022). "Of the five patients with NF1-associated gliomas belonging to the molecular low-grade group, four experienced stable disease and absence of tumor growth while on MEK inhibitor therapy at time of last clinical follow-up." (PMID 35945463, 2022). "Only two of the six NF1-associated gliomas that clustered with IDH-wildtype glioblastoma had the combination of chromosome 7 gain and chromosome 10 loss, both of which aligned with the mesenchymal subclass." (PMID 35945463, 2022). "EGFR (21%), PTEN (17%), and NF1 (12%) mutations in the high-glioma risk score group and CIC (28%), FUBP1 (11%), and NOTCH1 (10%) mutations in the low-risk score group were identified, and the mutation frequency of these genes was greater than 10%." (PMID 36311792, 2022). "MEK inhibition has emerged recently as a targeted therapeutic approach for NF1-associated tumors, and temozolomide is a standard chemotherapeutic agent for high-grade gliomas and is occasionally used to treat MPNST." (PMID 35740680, 2022). "Together, these findings highlight recurrently altered pathways in NF1-associated gliomas and help inform targeted therapeutic strategies for this patient population." (PMID 35945463, 2022). "Of the four patients with NF1-associated gliomas belonging to the molecular high-grade group, three demonstrated glioma progression during treatment with MEK inhibitor as a single agent." (PMID 35945463, 2022). "Gliomas of the optic pathways and brainstem usually occur during childhood and are linked to NF1 gene mutations." (PMID 35053664, 2022). "NF1-associated gliomas in the molecular high-grade group often had increased cellular density, higher Ki-67 labeling indices, and loss of p16 and/or ATRX expression on immunohistochemical evaluation compared to the molecular low-grade group." (PMID 35945463, 2022). "Second, the SEER program provided limited information about the genetics of central nervous system tumors, and NF-1 is believed to be associated with the survival of patients with OPGs." (PMID 35223473, 2022). "In parallel, MG highly expressing Cx3cr1 are led towards glioma by Cx3cl1, which is secreted by glioma cells with NF1 mutation." (PMID 34671362, 2021). "DNA methylation is an emerging factor in the classification of brain tumors and potentially in NF1-associated gliomas as well." (PMID 34885143, 2021). "The MES molecular subtype accounts for approximately 35% of all adult high-grade gliomas and is primarily characterised by the loss or deregulated expression of NF1." (PMID 35008787, 2021).
glioma (continued). "Children suffering from neurofibromatosis type 1 (NF-1) and tuberous sclerosis (TS), two cancer-predisposition syndromes, show a higher rate of low-grade gliomas." (PMID 33808415, 2021). "The polymorphism of cAMP synthetase, adenylate cyclase 8 (ADCY8), elevates the glioma risk in NF1 female patients, but reduces it in males." (PMID 34566848, 2021). "Although predisposition to LGG is more common, NF1 patients are also at risk for high grade gliomas." (PMID 33863389, 2021). "To study this inverse association between asthma and brain tumor incidence in a cancer predisposition syndrome in which atopic conditions reduce glioma incidence, we leveraged a genetically engineered mouse model of NF1-low-grade glioma of the optic pathway." (PMID 34880260, 2021). "NF1-associated low-grade gliomas, usually seen at younger ages, have very low mutation burden, with only a few somatic mutations." (PMID 33779771, 2021). "The choice of molecular inhibitor, e.g., BRAF, MEK or FGFR depends on the underlying biology, and so biopsy is essential prior to commencing such specific agents in non-NF1 associated pediatric low-grade glioma." (PMID 33532921, 2021). "It is reported that high-grade NF1 glioma exhibited frequent ATRX mutations, while a particular methylation subgroup of sporadic gliomas, the LGm6 subgroup, is enriched with ATRX mutations and assembles epigenetic profiles of NF1 glioma." (PMID 34566848, 2021). "Myelin vacuolization is of particular importance, as it is often difficult to differentiate this feature from NF1-associated gliomas in imaging." (PMID 33779771, 2021). "Although most NF1-related gliomas are classified as benign pilocytic astrocytomas, adult NF1 patients are at ~50-fold increased risk of developing malignant glioblastomas." (PMID 34604034, 2021). "They first proved that NF1 mutations act via the NF1–MAPK–FOSL1 axis in MES gliomas as they increase FOSL1 RNA and protein expression and therefore activate the expression of the MES gene signature and inhibit the non-MES gene signature." (PMID 35008787, 2021). "NF1-associated OPGs arise from glioma stem cells and astrocytes with bi-allelic inactivation of the NF1 gene in a microenvironment of stromal cells including microglia, neurons, and endothelial cells haploinsufficient for NF1." (PMID 34885143, 2021). "MEKi trametinib therapy of NF1 associated high grade gliomas is reported only in single NF1 adult cases: in a 24-year-old male with NF1 and treatment-refractory glioblastoma and in a 19-year-old male with NF1 and a recurrent mesencephalic glioblastoma." (PMID 33863389, 2021). "DNA methylation profiles indicate that NF1 associated gliomas belong to a poorly defined Isocitrate dehydrogenase 1 wild-type subgroup (LGm6, mesenchymal subtype) of sporadic gliomas." (PMID 33863389, 2021). "OPG is the most common NF1-associated central nervous system tumor, affecting 15–20% of the children with NF1." (PMID 33821340, 2021). "NF1-associated gliomas were found to have distinct genetic signatures, distinguishing them from those observed in sporadic gliomas, as well as noted to display different genetic landscapes when comparing low- vs. high-grade gliomas." (PMID 31906320, 2020).
glioma (continued). "While individuals with NF1 are at higher risk for developing low-grade gliomas compared to high-grade gliomas, their risk for high-grade glioma is increased by 50-fold when compared to the general population." (PMID 31906320, 2020). "Another glioma-related gene that has a key effect on the control of the microenvironment is NF1, which has been associated with the recruitment of TAMs in GBM and with an enriched immune transcriptome." (PMID 32570988, 2020). "Overall, few of the commonly associated glioma driver genes were mutated in the methylation cluster PA-like, and NF1 and SF3B1 were the only recurrently mutated genes in this cluster." (PMID 32555164, 2020). "For example, secreted factors from glioma cells that have transitioned to a mesenchymal subtype by loss of NF1 have increased capacity to attract microglia." (PMID 32642713, 2020). "Instead, combined mutations in TERTp, PTEN and NF1 are described for high-grade gliomas and are associated with an unfavorable prognosis." (PMID 32758285, 2020). "In summary, the NF1 tumor-predisposition syndrome is associated with a heterogenous pattern of gliomas with distinct genetic signatures which differ from sporadic gliomas." (PMID 31906320, 2020). "Loss-of-function mutations of CDKN2A and NF1 have been observed as drivers in a range of human gliomas including LGG and GBM." (PMID 32727536, 2020). "The rarity of DMGs H3 K27M-mutant in NF1 patients is underlined by a recent study where genomic profile of 59 gliomas (22 children, 33 adults) was evaluated." (PMID 32582540, 2020). "Our molecular and immunological understanding of NF1-associated gliomas is rapidly evolving, and biopsy is increasingly indicated not only for histologic confirmation, but also for molecular-targeted therapy." (PMID 32486389, 2020). "A promising agent is selumetinib, which has shown favorable results in phase II studies of NF1-associated low grade gliomas." (PMID 31906320, 2020). "As we enter the era of precision oncology, clinical trials of new drugs targeting the RAS/MAPK pathway are underway for NF1-associated gliomas, and other immunotherapies are under development." (PMID 31906320, 2020). "The most common glioma associated with NF1 is pilocytic astrocytoma, a WHO grade I tumor, with the optic pathway glioma being a hallmark lesion." (PMID 31906320, 2020). "In this circumstance, a germline NF1 mutation followed by a somatic mutation lead to the loss of heterozygosity of the NF1 gene, thus causing the development of glioma." (PMID 31677015, 2020). "For instance, NF associated high-grade glioma models have been established by coupling complete inactivation of NF-1 and PTEN genes." (PMID 33308182, 2020). "The association between NF1 and increased risk of malignant tumors has been widely described with the most commonly reported associations being gliomas and malignant peripheral nerve sheath tumors." (PMID 30962859, 2019). "Here, we show that NF1-loss in patient-derived glioma cells using shRNA increases self-renewal, heightens cell invasion, and promotes mesenchymal subtype and epithelial mesenchymal transition-specific gene expression that enhances tumorigenesis." (PMID 30967630, 2019). "We reported for the first time a high frequency of ATRX loss and ALT in high-grade and diffuse gliomas developing in NF1 patients, and more recent studies have also documented ATRX mutations in aggressive NF1-associated gliomas." (PMID 31462295, 2019). "It is believed that glioma cells undergo EMT-like activity that is associated with NF1 loss or dysregulation." (PMID 30967630, 2019).
glioma (continued). "Our findings are in agreement with published report whereby loss of NF1 by shRNA promoted glioma cell invasion and upregulation of EMT markers such as vimentin, SNAI, TWIST1, ZEB1, and ZEB2." (PMID 30967630, 2019). "In the ALT-positive glioma group, all 6 had pathogenic NF1 mutations, with a high VAF suggestive of LOH (n = 4) or a second mutation (n = 1)." (PMID 31462295, 2019). "For example, NF-1 deficiency in IDH-wild type glioma cells results in increased recruitment of macrophages." (PMID 31632393, 2019). "In summary, our data support an important role for ATRX/DAXX loss and acquisition of ALT with an aggressive biology in NF1-associated gliomas, as well as a molecular subset of NF1-associated MPNSTs." (PMID 31462295, 2019). "Inhibition of glutamine utilization via glutaminase inhibition has also been proposed for treatment of gliomas and NF1-deficient tumor cells." (PMID 29662612, 2018). "Tumor NF1 status strongly predicts the presence of tumor-infiltrating lymphocytes, and a recent mechanistic study showed that conditioned media from NF1-deficient glioma cells increases macrophage recruitment in vitro." (PMID 29643433, 2018). "In order to study the role of NF1 as a mediator of the tumor microenvironment in GBM, we examined how NF1 loss influences secreted factors from neoplastic cells by applying glioma cell line conditioned media to cytokine arrays." (PMID 29643433, 2018). "In our study, NF1 knockdown was associated with increased transcription and secretion of IL-8 in 2 of 3 glioma cell lines." (PMID 29643433, 2018). "This study is the first suggestion, to our knowledge, of a direct link between NF1 loss in glioma and production of CHI3L1 by neoplastic cells." (PMID 29643433, 2018). "Among the 16 cases, one patient with a germline NF1 mutation was initially diagnosed with a WHO grade II glioma with pilocytic features (HGG16) before recurring as a HGG." (PMID 29084603, 2017). "In NF1-associated low-grade gliomas, CXCL12 also serves as a paracrine factor that drives the growth of neoplastic Nf1−/− astrocytes." (PMID 28380429, 2017). "Using this approach, we demonstrate that optic gliomas generated by altering the germline Nf1 gene mutation, the glioma cell of origin, or the presence of co-existing genetic alterations represent molecularly-distinct tumors." (PMID 28881745, 2017). "In this regard, we recently leveraged a low-grade glioma mouse model of Neurofibromatosis type 1 (NF1)-associated optic glioma to identify and characterize low-grade glioma (LGG) cancer stem cells (LG-GSCs)." (PMID 26981778, 2016). "Using Nf1 genetically engineered animal model, a recent study has demonstrated that increased glioma risk in females with Nf1 is linked to a modifier gene and sexually dimorphic cAMP signalling." (PMID 27516813, 2016). "Recently, we provided human validation for a cooperating oncogenic role for cAMP in brain tumorigenesis when we found that SNPs in ADCY8 were correlated with glioma (brain tumor) risk in individuals with Neurofibromatosis type 1 (NF1)." (PMID 26283963, 2015).
glioma (continued). "The association between NF1 and malignant tumors has been widely described; the most common reported associations are with gliomas, malignant peripheral nerve sheath tumors (MPNST), leukemia and rhabdomyosarcoma." (PMID 25889501, 2015). "Even in autosomal dominant tumor predisposition syndromes, like neurofibromatosis-1 (NF-1), NF-1 inactivation results in increased astrocyte growth, but the augmented proliferation rate is actually unable to induce glioma formation." (PMID 25013812, 2014). "Mutations in the NF1 gene have long been known to predispose to glioma formation, as these tumors are part of the tumor spectrum of the NF syndrome." (PMID 21931722, 2011). "The association between NF-1 and tumors of neurogenic and neuroendocrine origin, such as meningiomas, gliomas and pheochromocytomas, is well known." (PMID 22018031, 2011). "The younger age at diagnosis in patients with NF1-associated high-grade gliomas could affect the better KPS and partially explain the longer survival." (PMID 40277798, 2025). "Gliomas other than pilocytic astrocytomas, also associated with NF1, display a worse prognosis." (PMID 41168866, 2025). "Furthermore, NF1 mutations enhance the proliferation of neural progenitor cells, providing a source of stem-like cells that fuel glioma growth." (PMID 40630952, 2025). "Moreover, NEU4 and GPR17 expression was enriched in the tumor cell clusters of both sporadic and NF1-associated low-grade gliomas (pilocytic astrocytoma)." (PMID 41497446, 2025). "Moreover, the mesenchymal subtype of glioma is associated with a high frequency of NF1 abnormalities, which are associated with immunosuppression and aggression." (PMID 39866232, 2025). "Recently, a study comprising 47 NF1-associated gliomas showed that those patients with low-grade gliomas, independently from morphological presentation (conventional pilocytic astrocytoma, diffuse astrocytoma, or ganglioglioma), presented with tumors in a single specific epigenetic cluster." (PMID 40277798, 2025). "This region also contains an NF1 coding sequence, the deletion of which leads to neurofibromatosis, a disease which is associated with an increased risk of developing tumors, including gliomas." (PMID 40076291, 2025). "HBS-101, a novel midkine inhibitor, reduced optic nerve proliferation, normalized RNFL thickness, and decreased the expression of tumor (Neu4, Gpr17) and TME (Ccl2, Ccl3, Ccl4, Ccl5) genes, supporting its continued development as a targeted therapy for pediatric NF1-associated glioma." (PMID 41497446, 2025). "We briefly introduce the terminology of the AI field and NF1-associated glial tumors." (PMID 41168866, 2025). "In the present study, increased FDG uptake was observed in gliomas with NF1 mut/loss." (PMID 40786409, 2025). "Identifying a change towards atypia in NF1-associated peripheral glial tumors is challenging." (PMID 41168866, 2025). "Typically NF1-associated low-grade gliomas present an indolent clinical course." (PMID 40277798, 2025). "Inactivating mutations in NF-1, found in a subset of gliomas, lead to persistent RAS signaling." (PMID 40362343, 2025). "Interestingly, NF1-deficient glioma xenograft, LN229, also was transduced at approximately 30% by one dose of AAV-K55-GFP." (PMID 41022755, 2025).